CRP (C-reactive protein)
Diseases named in the same sentence as CRP in open-access papers (continued):
Sharing a sentence is not in itself a finding about the gene and the disease.
eosinophilia (continued). "Initial laboratory findings showed elevated white blood cell counts, with eosinophilia (maximum of 6920 cells/μL), thrombocytosis (531,000 cells/μL), and elevated CRP (2.28 mg/dL)." (PMID 39963651, 2025). "While not specific to EVALI, laboratory tests can reveal clues like elevated white blood cell count, inflammation markers (like C-reactive protein), and possibly eosinophilia." (PMID 40427906, 2025). "Blood tests showed an eosinophilia of 1.2 × 109/L (NR 0.0–0.4) but a normal C-reactive protein of <0.3 mg/L (NR < 5.0), and Strongyloides spp." (PMID 40559730, 2025). "The bloodwork revealed eosinophilia (5.3x109/L), cholestasis (alkaline phosphatase 316 U/L and gamma-glutamyl transferase 195 U/L), and elevated C-reactive protein (4.53 mg/dL)." (PMID 39726513, 2024). "Eosinophilia was noted in the differential leukocyte count at 10.10%, and the C-reactive protein (CRP) level was elevated at 130, suggestive of a parasitic infection." (PMID 39650702, 2024). "Workup was remarkable for peripheral eosinophilia, hypergammaglobulinemia, and elevated C-reactive protein." (PMID 38774817, 2024). "Mild-to moderate eosinophilia (eosinophil count > 500 cell/mm3) was described in 44/50 (89%), and an increase in C-reactive protein levels was observed in 6/18 (33%) patients." (PMID 39518580, 2024). "On a biological level, the blood count revealed lymphopenia and slight eosinophilia, as well as the presence of an inflammatory syndrome with thrombocytosis, elevated sedimentation rate, and C-reactive protein, along with hyperferritinemia." (PMID 38983983, 2024). "Finally, a comparative study of 166 patients with blood eosinophilia (>1.000 cells/μL) and systemic manifestations demonstrated that CRP level was a sound diagnostic biomarker that could accurately differentiate between HES and EGPA, with low levels (<36 mg/L) suggestive of HES." (PMID 37215720, 2023). "Blood analysis revealed eosinophilia; elevated erythrocyte sedimentation rate; and elevated levels of C-reactive protein, total immunoglobulin E, and thymic and activation-regulated chemokines." (PMID 38053199, 2023). "Hypergammaglobulinemia, elevated CRP and eosinophilia are found in the active stages of linear morphea, while the latter is also seen in the generalized type." (PMID 36860340, 2023). "A systemic work-up revealed a positive Echinococcus ELISA IgG with a value of 1.3, eosinophilia of 5.70% (0.41 × 109), and elevated C-reactive protein and erythrocyte sedimentation rate of 47 mg/L and 93 mm/hr, respectively." (PMID 36051405, 2022). "She had mild eosinophilia of 0.88 (0.00–0.60 × 109/L), a slightly raised C-reactive protein (CRP) of 7.5 (0–5.0 mg/L), and a raised troponin I of 1236 (0–18 ng/L)." (PMID 36298637, 2022). "For instance, patients with eosinophilia had lower CRP levels, a milder clinical course, and better disease outcomes compared with patients without eosinophilia." (PMID 35632823, 2022). "Common laboratory abnormalities include neutrophilia, eosinophilia, and elevated inflammatory markers (elevated sedimentation rate and C-reactive protein)." (PMID 35573534, 2022). "Half displayed high sputum and blood eosinophilia, elevated FeNO and low CRP; the other half sputum neutrophilia, higher CRP and lower FeNO." (PMID 36149782, 2022). "Laboratory values revealed elevated CRP of 7 mg/dl (normal <0.5 mg/dl) and significant eosinophilia of 4570/mm3 (normal 300–500/mm3)." (PMID 33787639, 2021). "Laboratory examinations revealed eosinophilia, elevated hepatic enzymes, and slightly raised C-reactive protein." (PMID 34162437, 2021). "In the generalized form, the lesions are diffusely distributed, and patients present with malaise, high-grade fever, neutrophilic leukocytosis, peripheral eosinophilia, and elevated C-reactive protein." (PMID 34884596, 2021). "After 2 months, minimal clinical improvement was apparent, although peripheral eosinophilia normalized and CRP decreased to 1.6 mg/L." (PMID 33787639, 2021).
eosinophilia (continued). "Using multivariable logistic regression, odds ratios were calculated and adjusted for previous eosinophilia, sex, age, year, month, CRP and comorbid conditions." (PMID 31360453, 2019). "Using multivariable logistic regression, odds ratios (OR) were calculated and adjusted for sex, age, year, month, eosinophilia, comorbid conditions and C-reactive protein (CRP)." (PMID 24914777, 2014). "In contrast, the clinical utility of CRP monitoring during clozapine titration to prevent clozapine-induced inflammation is well-established, with elevated CRP levels potentially predicting subsequent eosinophilia." (PMID 39680690, 2026). "Laboratory findings may reveal peripheral eosinophilia, elevated CRP, and an increased erythrocyte sedimentation rate." (PMID 41393563, 2025). "The incubation periods of the rashes ranged from 1 week to 2 months, and some patients also exhibited other symptoms like elevated white blood cell count, eosinophilia, increased C-reactive protein and lactate dehydrogenase levels, lymph node enlargement, fever, liver damage, and nail dystrophy." (PMID 41239639, 2025). "Blood tests showed high eosinophilia, high C-reactive protein (CRP), and high liver enzymes levels." (PMID 36778654, 2023). "Laboratory tests revealed eosinophilia (21%) and elevated C-reactive protein (CRP; 67 mg/L)." (PMID 33470957, 2021). "One developed elevated liver enzymes with eosinophilia and elevated CRP (drug reaction with eosinophilia and systemic symptoms (DRESS syndrome), one developed digit hyperesthesia after 7 months treatment, and one person developed hemolytic anemia (hemoglobin 9.7 g/dl = 6 mM) with 72% reticulocytes." (PMID 33669324, 2021). "Laboratory findings included peripheral eosinophilia of >3000/mm3 and CRP 17.8 mg/L." (PMID 33787639, 2021). "We believe that the difference of ESR levels between the two groups was mainly due to the different distribution of serum IgG and IgG4, as patients with eosinophilia had higher serum IgG, IgG4, while with a similar level of CRP compared to patients with normal eosinophil counts." (PMID 31712579, 2019). "Although more and more of the previously identified risk factors can be linked with the other phenotypes, ARAD (neutrophilia, IL-1β, IL-8, IL-6, and TNF-α, CRP) and RAS (eosinophilia, CRP), protein profiles observed in this and previous reports 27 do not show significant changes." (PMID 24750386, 2014). "These risk estimates did not change when eosinophilia, CRP, and comorbidities were included in the models." (PMID 24914777, 2014). "In addition, infection indexes include leukocyte (WBC), neutrophil (Neut), lymphocyte (Lymph), eosinophilia (EO), C-reactive protein (CRP), procalcitonin (PCT), interleukin-6 (IL-6), and erythrocyte sedimentation rate (ESR) of all the negative samples were collected." (PMID 35651750, 2022). "Adjustment for eosinophilia, CRP and comorbidities did not alter any of the risk estimates." (PMID 24914777, 2014). "Elevated total IgG and IgE, peripheral eosinophilia, ESR (Erythrocyte Sedimentation Rate), and C -reactive protein were found." (PMID 39839693, 2025). "The eruption typically occurs in association with systemic symptoms, most notably fever, neutrophilic leukocytosis, elevated C-reactive protein (CRP), and, in one-third to half of cases, mild eosinophilia." (PMID 40922885, 2025). "Laboratory workup revealed a mildly elevated C-reactive protein (CRP) level of 10 mg/dL and mild eosinophilia of 0.6x109/L, likely reflecting localized inflammation." (PMID 40917922, 2025). "Elevated IgG and IgE, peripheral eosinophilia, raised Erythrocyte Sedimentation Rate (ESR) and C-reactive protein (CRP) level, positive antinuclear antibodies (ANAs) and Rheumatoid Factor (RF), and hypocomplementemia are additional common findings." (PMID 40723081, 2025). "The percentage of patients with peripheral eosinophilia was found to be significantly higher in patients with DEP as were the leukocyte counts and C-reactive protein values." (PMID 37384075, 2023).
eosinophilia (continued). "Initial laboratory results showed elevated CPK, alanine aminotransferase (ALAT), and lactate dehydrogenase (LDH) and slightly elevated C-reactive protein (CRP) and erythrocyte sedimentation rate (ESR) in combination with an eosinophilia." (PMID 26115699, 2015). "Laboratory investigations revealed a normal creatine kinase (CK), elevated troponin T at 2.74 ug/L, C– reactive protein (CRP) at 140 mg/L (normal: 0–8), and eosinophilia at 3.92×105/L." (PMID 24344829, 2013). "Although maximum body temperature and peak CRP levels tended to be higher in patients with eosinophilia, these differences were not statistically significant." (PMID 39680690, 2026). "CRP lacks specificity, eosinophil counts vary by phenotype, and FeNO primarily reflects airway eosinophilia without capturing systemic inflammation." (PMID 40546825, 2025). "His workup revealed hyperleukocytosis with neutrophilia, eosinophilia, and hepatitis along with electrolytic abnormalities and elevated C-reactive protein without a definitive source of infection." (PMID 40041650, 2025). "Hematological tests revealed the following results: hemoglobin: 13.6 g/dL, white blood cell count: 11,500 cells/μL, eosinophils: 4 % (eosinophilia not present), and C-reactive protein (CRP) within normal limits." (PMID 39731794, 2025). "This study highlights that CEP with eosinophilia in BAL fluid can be distinguished from the other four ILDs by several parameters, including BAL eosinophilia, elevated BAL ILC3 frequency, low serum KL-6 levels, high CRP levels, and elevated peripheral blood WBC counts." (PMID 39858516, 2025). "Repeat blood tests around 2 weeks after the second dose of ivermectin showed persisting eosinophilia of 1.1 × 109/L but again a C-reactive protein of <0.3 mg/L and negative Strongyloides spp." (PMID 40559730, 2025). "Laboratory investigations revealed eosinophil percentage (17.60%, reference range 0.4–8%), blood eosinophilia (1.52 × 109/L, reference range < 0.5 × 109/L), erythrocyte sedimentation rate (ESR) (19 mm/h, reference range < 15 mm/h), C-reactive protein (CRP) (15.20 mg/L, reference range < 10 mg/L)." (PMID 41137258, 2025). "Laboratory analysis demonstrated peripheral eosinophilia (3090/μL) and an elevated C-reactive protein (CRP) level of 19.53 mg/dL with no further alterations." (PMID 39606502, 2024). "Lab tests, though not definitive for morphea diagnosis, often reveal abnormalities like peripheral blood eosinophilia and changes in aldolase, creatinine kinase, lactate dehydrogenase (LDH), erythrocyte sedimentation rate (ESR), and C-reactive protein (CRP) levels." (PMID 38919251, 2024). "Nevertheless, there was no statistical significance of elevated C-reactive protein levels between patients who developed eosinophilia compared to those who did not." (PMID 38610788, 2024). "Our case presentation did not observe peripheral eosinophilia or hypersensitivity reactions; however, our patient had elevated inflammatory markers such as ferritin and c-reactive protein." (PMID 35663660, 2022). "Systemic inflammatory markers were elevated, including CRP and white blood cell count with neutrophilia but no eosinophilia." (PMID 35152886, 2022). "The presence of blood eosinophilia at the end of daptomycin treatment was significantly higher in DEP cases than in controls (82% and 16%, respectively; p < 0.001), as well as leucocyte counts and C-reactive protein values were also higher in DEP cases." (PMID 33923382, 2021). "After the patient was started on cow’s milk feeds, he remained asymptomatic, and laboratory analyses showed no elevation of white cell count or CRP, and no eosinophilia in the blood or stool." (PMID 22943656, 2012). "First, overt eosinophilia was absent (0.1%) despite marked systemic inflammation (CRP 135 mg/L)." (PMID 41356128, 2025). "However, there was only partial clinical improvement, as peripheral eosinophilia count did not regress and CRP levels continued to rise." (PMID 33787639, 2021).
eosinophilia (continued). "CRP was elevated at 4.28 mg/dl, without peripheral eosinophilia." (PMID 33787639, 2021). "He had no peripheral eosinophilia but had high C-reactive protein and procalcitonin levels." (PMID 34552804, 2021). "CRP levels increased mildly to 0.7 mg/dl, with no peripheral eosinophilia." (PMID 33787639, 2021). "Routine blood tests may reveal nonspecific inflammatory trends such as eosinophilia, deranged liver function tests, and raised CRP and erythrocyte sedimentation rate (ESR)." (PMID 33106164, 2020). "Other laboratory tests (either organ-dependent: creatininemia, liver or pancreatic tests, or non-specific: CRP, complement, eosinophilia, or IgE elevation) were abnormal before RTX in 23 patients and their improvement or normalization occurred in 91.3% (n = 21) of cases." (PMID 28915275, 2017). "Treatment with IP results in eosinophilia and an increase of CD4 cells but not in an increase of IL-6 or CRP." (PMID 22114899, 2011).
gastric cancer (136 papers, 1982 to 2025). A primary or metastatic malignant neoplasm involving the stomach. "Some studies have shown that lymphocytes (L) and C-reactive protein (CRP) are associated with lower survival rates in gastric cancer." (PMID 41357197, 2025). "Higher levels are linked to low hemoglobin and albumin and elevated C-reactive protein in gastric cancer." (PMID 39859417, 2025). "A 55‐year‐old woman complained of recurrent gastric carcinoma, which was associated with chronic gastritis and high systemic inflammatory markers (elevated CRP and IL‐6)." (PMID 41179371, 2025). "For example, an elevated C-reactive protein/albumin (CRP/albumin) ratio has been traditionally associated with poor outcomes in septic patients, as well as in cases with hepatocellular, esophageal or gastric cancers." (PMID 39061143, 2024). "The combination of serum albumin and C-reactive protein (CRP) is a useful risk factor for postoperative complications and a prognostic factor postoperatively for long-term survival in patients with gastric cancer." (PMID 39594844, 2024). "Chronic inflammation measured based on TNF-a, CRP, and IL-6, among others, is highly correlated with an increased risk of gastric cancer; those measurements can be practical in predicting gastric cancer development at very early stages." (PMID 38068839, 2023). "In summary, the results of our study suggest that postoperative CRP/Alb ratio is a novel independent risk factor for predicting prognosis of gastric cancer." (PMID 37735699, 2023). "Some studies have reported that lymphocytes, neutrophils, and C-reactive protein (CRP) are associated with disease progression in patients with gastric cancer." (PMID 37361569, 2023). "Six variants were found downstream of the CRP gene, which is an inflammatory biomarker closely associated with prognosis in lung and gastric cancers, as well as those involving PD1." (PMID 36011407, 2022). "As an inflammation hallmark and direct target of IL-6 signaling, CRP is closely related to progression in a wide variety of cancers including gastric cancer." (PMID 33144870, 2020). "NLR is one among a spectrum of seven inflammation-based prognostic biomarkers associated with poor survival in gastric cancer, including CRP, albumin, Glasgow prognostic score, platelet-lymphocyte ratio, neutrophil-platelet score and lymphocyte-monocyte ratio." (PMID 29949048, 2018). "Elevated C-reactive protein/albumin ratio was an independent predictor for postoperative complications following gastrectomy of gastric cancer, and the diagnostic accuracy was higher than C-reactive protein alone." (PMID 29065877, 2017). "Elevated CRP has been associated with progressive disease or an advanced stage and a worse survival rate for gastric cancer patients." (PMID 21811552, 2011). "Therefore, postoperative CRP/Alb ratio is an independent risk factor for predicting the prognosis of gastric cancer." (PMID 37735699, 2023). "High serum C-reactive protein (CRP) was found to be associated with poor prognosis in kinds of solid tumors, however, its role in the recurrent gastric cancer (RGC) is unknown." (PMID 27303917, 2016). "Stomach cancer was marginally positively associated with hs-CRP." (PMID 21368452, 2011). "A notable study investigating the role of CRP in overall cancer and site-specific cancers found that a higher concentration of CRP was linked to an increased risk of developing overall cancer, with positive linear associations observed in esophagus and stomach cancers." (PMID 40565234, 2025). "However, high IL-6 and CRP levels were related to advanced stage, including distant metastasis, in this study, and elevated IL-6 levels were associated with poor outcomes in cases of gastric cancer." (PMID 19457231, 2009). "We selected CRPmax as the primary endpoint for the phase II portion of the study, because our previous large-scale cohort study demonstrated that the postoperative CRP level was a good predictor of prognosis in patients with gastric cancer." (PMID 40638018, 2025).